WNT5A (Wnt family member 5A)
Diseases named in the same sentence as WNT5A in open-access papers (continued):
Sharing a sentence is not in itself a finding about the gene and the disease.
periodontitis (10 papers, 2012 to 2025). An acute or chronic inflammatory process that affects the tissues that surround and support the teeth. "Within each patient diagnostic category, total WNT-5a was similar among all types of sites in patients with periodontitis (p = 0.11) and in patients diagnosed with gingivitis (p = 0.32)." (PMID 34440994, 2021). "Additional regression analysis controlling for the effect of age confirmed these results that chronic periodontitis was associated with increased mRNA levels of Wnt5a (p<0.001)." (PMID 22485170, 2012). "In early periodontitis, Wnt5a was overexpressed in periodontal ligament tissue and regulated the CaMKII pathway, which should be involved in maintaining periodontal homeostasis." (PMID 35464198, 2022). "Wnt5a has been acknowledged to participate in the pathogenesis of periodontitis, take part in the development of periodontium, promote fibrinogenesis, and moderate osteogenesis in periodontal stem cells." (PMID 35464198, 2022). "Within the periodontitis and gingivitis patient groups, WNT-5a amounts were similar between the different site groups." (PMID 34440994, 2021). "In conclusion, Sclerostin and WNT-5a were detectable in the GCF of periodontitis, gingivitis and healthy patients." (PMID 34440994, 2021). "The WNT-5a total amounts in the GCF of gingivitis sites were significantly lower than in periodontitis sites." (PMID 34440994, 2021). "In the present study, WNT-5a total amounts were significantly elevated at periodontitis sites when compared to gingivitis." (PMID 34440994, 2021). "The findings of our investigation also showed that the WNT-5a levels were similarly high between periodontitis and healthy sites." (PMID 34440994, 2021). "Irrespective of the overall diagnosis of each patient, total amounts of WNT-5a was similarly high in periodontitis sites (2.37 ± 1.31 ng) and healthy sites (2.04 ± 1.18 ng) while lower in gingivitis sites (1.36 ± 0.67 ng) (p = 0.03)." (PMID 34440994, 2021). "In the gingiva of chronic periodontitis patients, Wnt5a is expressed significantly higher than in periodontally healthy patients." (PMID 34440994, 2021). "The expression of Wnt5a is also significantly increased in gingival tissues of aggressive periodontitis when compared to tissues from chronic periodontitis." (PMID 34440994, 2021). "Meanwhile, periodontitis related protein Wnt5a and cytokines were significantly higher after stimulated with H. pylori." (PMID 27602578, 2016). "Using RT-PCR, we demonstrated that Wnt5a mRNA expression was up-regulated in chronic periodontitis tissue as compared to healthy control tissue." (PMID 22485170, 2012). "Wnt5a mRNA was significantly up-regulated in chronic periodontitis tissues as compared to healthy control tissues." (PMID 22485170, 2012). "The purpose of this study was to evaluate the levels of Wnt5a expression in chronic periodontitis tissue and investigate the modulation of Wnt5a expression by periodontopathic bacteria." (PMID 22485170, 2012). "In this study, we investigated the levels of Wnt5a expression in chronic periodontitis tissues, and the modulation of Wnt5a expression by periodontopathic bacteria." (PMID 22485170, 2012). "The mean relative mRNA level of Wnt5a was significantly higher in the periodontitis group (1.44±0.26) than in the control group (1.00±0.22; p<0.001)." (PMID 22485170, 2012). "In conclusion, we confirmed that GMSC-Exo could suppress the inflammatory response of PDLSCs by regulating the expression of NF-κB signaling and Wnt5a, which paves the way for the establishment of a therapeutic approach for periodontitis." (PMID 35464198, 2022). "WNT-5a levels in GCF depend on the level of disease of periodontitis sites." (PMID 34440994, 2021). "Considering the current knowledge in the field, we hypothesized that the total amount of Sclerostin and WNT-5a in GCF differ at sites with (i) chronic periodontitis, (ii) gingivitis and (iii) healthy periodontal tissues." (PMID 34440994, 2021).
periodontitis (continued). "When all periodontitis (n = 51), gingivitis (n = 12) and healthy (n = 45) sites were analyzed regardless of the patient diagnosis, periodontitis sites demonstrated significantly elevated WNT-5a total amounts (p = 0.03) when compared to gingivitis sites." (PMID 34440994, 2021). "It had been known that Wnt5a could be expressed by some immune cells including almost all antigen-presenting cells and it has been considered as one of the key molecular in chronic periodontitis recently." (PMID 27602578, 2016). "The result suggested that in response to periodontitis, the genes of Wnt superfamily may be activated by H. pylori and H. pylori may enhance the expression of Wnt5a and induce the development of periodontitis." (PMID 27602578, 2016). "The study proved that GMSC-Exos reduced the inflammatory immune response of periodontitis by regulating the Wnt5a-mediated RANKL pathway, and pretreatment of GMSC-Exos with TNF-α could upregulate miR-1260b to further inhibit Wnt5a, thereby contributing to the resolution of inflammation." (PMID 39184549, 2024). "For example, EVs derived from human GMSCs (GMSC-EVs) could inhibit the inflammatory response of PDLSCs by regulating the expression of NF-κB signaling and Wnt5a, which restored the regenerative potential of PDLSCs and promoted periodontal tissue regeneration in patients with periodontitis." (PMID 36678909, 2023). "Therefore, Wnt5a might be a periodontitis-related protein and could suggest the potential periodontal destruction." (PMID 27602578, 2016). "The “strict” periodontitis subgroup produced median levels of SOST (140.00 pg), WNT-5a (2.4 pg) and TNF-α (44.7 pg) compared with the “strict” healthy group who exhibited levels of SOST (78.9 pg), WNT-5a (1.29 pg) and TNF-α (27.3 pg)." (PMID 35453967, 2022). "In gingivitis sites, the WNT-5a levels are low, as the osteoclastogenic activity is not as pronounced as in periodontitis sites, where the osteoclastic activity is sustained." (PMID 34440994, 2021). "We show that Wnt5a mRNA was significantly up-regulated in chronic periodontitis tissue when compared to non-periodontitis tissue." (PMID 22485170, 2012). "There have been no previous reports on Wnt5a expression in periodontitis tissue, and only few study reported the molecular mechanisms of Wnt5a expression in LPS-stimulated monocytic cells." (PMID 22485170, 2012).
basal cell carcinoma (9 papers, 2009 to 2021). A carcinoma involving the basal cells. "Although from a different cancer type, the finding that macrophage-derived WNT5A causes regression of basal cell carcinoma either indicates a complex action of macrophage-derived WNT5A and/or that our knowledge is limited regarding its functional effect(s)." (PMID 30171384, 2018). "Wnt5A is known to be a Shh target in the murine hair follicle and in basal cell carcinomas; thus, we set out to test whether Shh signalling also regulates Wnt5A expression in the forebrain." (PMID 19732418, 2009). "Based on these gain- and loss-of-function experiments, we suggest that Wnt5A is unlikely to be a direct transcriptional target of Shh signalling in the thalamic primordium, unlike in the hair follicle or in basal cell carcinomas." (PMID 19732418, 2009). "The target gene WNT5A of ENSCHIG00000000774 was involved in seven signaling pathways, such as the Wnt signaling pathway, basal cell carcinoma, and HTLV-I infection." (PMID 34249080, 2021). "The upregulation of WNT5a is worth mentioning because abnormal WNT5a signaling facilitates invasion by different tumor types and its expression was found to be upregulated in cutaneous squamous cell carcinoma (SCC) and basal cell carcinoma (BCC)." (PMID 34830328, 2021). "However, the expression and distribution of Wnt5a in cutaneous squamous cell carcinoma (SCC) and basal cell carcinoma (BCC), as well as the effect of Wnt5a on keratinocyte migration has not been studied in detail to date." (PMID 22384081, 2012).
heart failure (9 papers, 2018 to 2025). Inability of the heart to pump blood at an adequate rate to meet tissue metabolic requirements. "Clinically, low SFRP5 (or high Wnt5a/SFRP5 ratio) is associated with worse outcomes in heart failure and acute MI." (PMID 41465371, 2025). "Wnt5a is elevated in the serum and myocardium of heart failure patients and associated with cardiac dysfunction." (PMID 34564708, 2021). "Ginsenoside Rd increases reticulin secretion in adipose tissue via TBK1-AMPK and enhances mitochondrial biogenesis in heart failure through the Wnt5a/Ca2+ pathway." (PMID 39141645, 2024). "In this review, we will briefly summarize the previous findings on the role of Wnt signaling pathways in heart development and diseases, and then focus on the role of Wnt5a signaling in heart failure progression." (PMID 38709417, 2024). "This study brings to light the pivotal role of cardiomyocyte-derived Wnt5a in heart failure progression in response to pressure overload." (PMID 38709417, 2024). "Wnt5a has been reported to be elevated in the serum or myocardium of heart failure patients, and the level is positively related to cardiac dysfunction." (PMID 34564708, 2021). "Although the precise mechanism for Wnt5a-mediated cardiac dysfunction remains unclear, it is speculated that activation of mechanosensitive genes contributes to the progression of heart failure following pressure overload." (PMID 38709417, 2024). "High expression of Wnt5a (Wnt family member 5a) may promote myocardial inflammation and fibrosis, thereby contributing to heart failure progression." (PMID 34925046, 2021). "A recent study reported that Wnt5a was significantly increased in the serum and myocardium of patients with heart failure and decreased after left ventricular assist device therapy, implying that Wnt5a may be an ideal molecular target for CHF treatment." (PMID 34925046, 2021). "Increasing evidence suggests that miR-223 upregulates Wnt5a expression and miR-223 can be found in exosomes, hence Wnt5a regulation in cardiac failure may involve exosomal trafficking." (PMID 29564334, 2018). "Patients with heart failure demonstrated a significantly lower median SFRP5 concentration relative to patients with arrhythmias, with insignificant differences regarding WNT5a and STAT5A expressions between patients with different cardiac diseases." (PMID 41465371, 2025). "Wnt5a induces IL-6 and TIMP-1 by activation of ERK in CFs, resulting in cardiac inflammation and subsequent heart failure progression." (PMID 34564708, 2021). "The findings suggest that non-canonical Wnt5a-YAP signaling axis mediates mechanotransduction in cardiac myocytes and contributes to the transition to heart failure." (PMID 38709417, 2024).
lung diseases (9 papers, 2011 to 2026). "If it is known, for example, that a patient has the reference RBMS3 allele and the alternate WNT5A allele, this might indicate a highly likelihood of developing severe SSc-related lung disease, and testing and treatment of lung disease could be started early and aggressively." (PMID 31694854, 2020). "Wnt5a is known to stimulate the PCP pathway and this ligand is of particular interest in regenerative lung biology because of its association with lung diseases and its role in the alveolar stem cell niche." (PMID 38476262, 2024). "In the following, we will take a detailed look at the role of Wnt5A in the remodeling and modulation of inflammatory and immunological processes in different lung diseases." (PMID 36658268, 2023). "All in all, the role of Wnt5A in lung diseases is still inconsistent." (PMID 36658268, 2023). "We chose to examine the modulation of WNT5A because it has been implicated in several pulmonary disorders and has not been studied in the context of VILI in healthy animals." (PMID 21935365, 2011). "While WNT5a is, indeed, essential for normal lung development and homeostasis, and is dysregulated in multiple lung diseases, little to no information is available regarding the expression or potential function of WNT5a isoforms in normal or diseased lungs." (PMID 42121944, 2026). "For example, rather than attempting to reduce WNT5A expression globally, a specific targeting of its interaction with RBMS3 may provide a novel approach to treating SSc-related lung disease without widespread off-target effects." (PMID 31694854, 2020).
lymph node metastasis (9 papers, 2013 to 2025). "The pT factor; lymph node metastasis; and expression of β-catenin, E-cadherin, and Wnt5a were significantly associated with the CSS." (PMID 41008809, 2025). "Using this optimized IRS approach and adjusting for clinically relevant factors (sex of the patients, TNM stage, lymph node metastasis), we performed a multivariate analysis of low-risk (high WNT5A expression) and high-risk (low WNT5A expression) patients." (PMID 37998393, 2023). "Wnt5a: The expression was significantly correlated with the pT factor, lymph node metastasis, distant metastasis, and a higher TNM stage." (PMID 41008809, 2025). "The results revealed that high WNT5A expression was positively correlated with the depth of invasion, lymph node metastasis, distant metastasis, and TNM stage." (PMID 37173306, 2023). "Wnt5a expression in ER-positive breast cancer correlated significantly with lymph node metastasis, nuclear grade, and lymphatic invasion." (PMID 29765514, 2018). "Additionally, high expression levels of WNT5a WNT5a significantly correlated with lymph node metastasis, nuclear grade, and lymphatic invasion, and recurrence-free survival (RFS) was shorter in BC patients with WNT5a expression than in those without." (PMID 33260642, 2020). "In addition, our results indicate that Wnt5a-positivity strongly correlated with the presence of lymph node metastasis, lymphatic invasion, vessel invasion, and nuclear grade in ER-positive breast cancer." (PMID 29765514, 2018). "Wnt5a expression had a close relationship with histological grade, FIGO stage, and lymph node metastasis (P = 0.005, P = 0.022, and P = 0.037, resp)." (PMID 30079293, 2018). "Analysis of 153 ER-positive cases revealed a significant difference between Wnt5a-positive and negative breast cancer in the presence of lymph node metastasis (P < 0.001), nuclear grade (P = 0.004), and lymphatic invasion (P = 0.002)." (PMID 29765514, 2018). "The methylation was discovered in 9 of 36 (25%) FIGO stage I~II and in 22 of 43 (51.16%) FIGO stage III~IV; Wnt5a was methylated in 21 of 41 (51.22%) carcinomas with lymph node metastasis, while 10 of 28 (26.32%) tumors without lymph node metastasis." (PMID 30079293, 2018). "Moreover, patients with ESCC presenting lymph node metastasis (N1–3) and a high American Joint Committee on Cancer (AJCC) seventh stage (stages III/IV) had higher WNT5A expression than those without lymph node metastasis (N0) and with a low seventh edition AJCC stage (stages I/II) (P < 0.001)." (PMID 35595735, 2022).
cervical carcinoma (8 papers, 2013 to 2023). A carcinoma arising from either the exocervical squamous epithelium or the endocervical glandular epithelium. "In cervical cancer, silencing FZD6 function caused delayed cellular proliferation, invasion, and EMT transition through HOXC13/WNT5A/FZD6 axis." (PMID 35237656, 2022). "From this data, we selected Wnt signaling pathway to study further because as Wnt5A overexpressed and has been correlated with cervical carcinoma." (PMID 35230971, 2022). "Additionally, HPV infected cervical cancer is shown to alter expression of miRNAs targeting WNT5A and FZD6." (PMID 35850748, 2022). "Various genes, namely GLS, CD36, WNT5a, HRAS, DDB2, PIK3R2, and CDH2 were found to be differentially highly expressed in primary cervical cancer samples of patients who developed distant recurrence." (PMID 35087740, 2021). "Namely, GLS, CD36, WNT5a, HRAS, DDB2, PIK3R2, and CDH2 were significantly DE between cervical cancer without recurrence and cervical cancer with distant recurrence." (PMID 35087740, 2021).
endometrial carcinoma (8 papers, 2011 to 2024). A malignant tumor arising from the epithelium that lines the cavity of the uterine body. "In contrast, not upregulation but downregulation of WNT-4, WNT-2, WNT-3, and WNT-5A was found to be important for endometrial cancer development." (PMID 37176048, 2023). "Based on the research conducted as part of this study, it was observed that there is a silencing in the expression of WNT5A, compared to the control, in endometrial cancer samples." (PMID 33917330, 2021). "The WNT4 mRNA level was lower while WNT2, WNT3, and WNT5A mRNA levels were higher in endometrial carcinoma in comparison to normal endometrium." (PMID 26366420, 2015). "As reported in earlier research, WNT5A could be considered as a potential marker of molecular changes that take place during endometrial cancer development." (PMID 39872660, 2024). "The presumed ligand for ROR2 in endometrial cancer is Wnt5a." (PMID 33494187, 2021). "Also WNT2, WNT3, WNT4, and WNT5A genes expression was higher in normal human primary epithelial and stromal endometrial cultures compared to endometrial carcinoma cell lines, what suggest their participation in endometrial neoplasia." (PMID 26366420, 2015).
esophageal squamous cell carcinoma (8 papers, 2012 to 2022). Esophageal squamous cell carcinoma (ESCC) is a type of esophageal carcinoma (EC) that can affect any part of the esophagus, but is usually located in the upper or middle third. "ROR1 strongly associates with ROR2, making up the receptor for Wnt5a signaling and activates RhoA through Daam1 in esophageal squamous cell carcinoma (ESCC) and glioblastoma." (PMID 35625853, 2022). "During esophageal squamous cell carcinoma pathogenesis, Wnt5a is frequently silenced by promoter methylation and antagonizes the Wnt/β-catenin pathway to exhibit tumor suppressor properties." (PMID 24944588, 2014). "STAT3 expression was upregulated by the Wnt3a, Wnt5a and Wnt6 ligands in cultured mouse embryonic stem cells, and by constitutively activate β-catenin in esophageal squamous cell carcinoma." (PMID 23056515, 2012). "On the contrary, ectopic expression of Wnt5a inhibited clonogenicity and motility of esophageal squamous cell carcinoma (ESCC) cells through antagonizing the Wnt/β-catenin pathway." (PMID 27571105, 2016). "Similarly, WNT-5A promoter hypermethylation is also observed in the esophageal squamous cell carcinoma (ESCC) tissues." (PMID 26514730, 2016).
gastric tumor (8 papers, 2014 to 2024). "We find that WNT5A expression is higher in gastric CAFs than in the gastric tumor cell line AGS and surrounding normal fibroblasts, which has been suggested previously." (PMID 37722040, 2023). "Suppression of UBE2T also inhibits gastric tumor invasion and metastasis via the WNT signal pathway by inhibiting WNT5A and WNT7B, which in turn promotes GSK3B expression, activates β-Catenin, and inhibits the key oncogene c-Myc." (PMID 28427240, 2017). "We hypothesized that in this way, the ROR2-low cells, like the gastric tumor cells AGS, could increase their responsiveness to fibroblast-produced WNT5A as they are receiving a functional receptor." (PMID 37722040, 2023). "To evaluate whether Wnt5a was engaged in macrophage chemotacxis, we investigated the effect of Wnt5a on the expression of CCL2 which was involved in macrophage recruitment in gastric tumor." (PMID 24416340, 2014). "Wnt5a, which primarily activates the non-canonical pathway, is up-regulated in human gastric tumours, however, this is not observed in cultured human GC cell lines (OKAJIMA, TMK1, MKN7, MKN28, MKN74 and KATOIII) suggesting the source of Wnt5a is from stromal cells." (PMID 27196929, 2016). "Furthermore, immunostaining of Wnt5a and P-ERK in these 50 primary gastric tumors revealed a negative correlation in expression (r = −0.288, P < 0.05)." (PMID 25779663, 2015).